AKT3 (AKT serine/threonine kinase 3)
Diseases named in the same sentence as AKT3 in open-access papers (continued):
Sharing a sentence is not in itself a finding about the gene and the disease.
melanoma (continued). "Thus, AKT3, HDAC9, TCF12, and LEF1 were differentially expressed in the melanoma specimens, tracking with CD271 enrichment." (PMID 31118427, 2019). "Myristoylated AKT3 has also been shown to partially protect melanoma cells from BRAF-inhibitor induced apoptosis without promoting MAPK activity." (PMID 30237495, 2018). "It is therefore not surprising that AKT3 has been identified as a therapeutic target for treating patients with malignant melanoma and indeed there are AKT inhibitors in clinical trials." (PMID 25595898, 2015). "Importantly, when AKT3 was silenced by siRNA (siAKT3) in ME1402 and MM200 VGP melanoma cells total AKT protein was undetectable and this corresponded with a decrease in TBX3 protein levels." (PMID 25595898, 2015). "Together these results suggest that AKT3 was the predominant active isoform in our melanoma cell lines and that it may be responsible for upregulating TBX3 in a subset of these melanoma cell lines." (PMID 25595898, 2015). "To explore whether AKT3 was therefore responsible for upregulating TBX3 levels, we firstly performed qRT-PCR to confirm that it was the predominant AKT isoform in our melanoma cell lines." (PMID 25595898, 2015). "PTEN-negative or AKT3-overexpressing melanomas do not undergo apoptosis in response to BRAF inhibition and do not upregulate pro-apoptotic protein BIM." (PMID 24743024, 2014). "For example, AKT3 promotes the survival of 40–60% non-hereditary melanoma cells and the development of malignant melanoma; in addition, it plays an important oncogenic role in triple negative breast cancer (TNBC), colorectal cancer (CRC), invasion and metastasis of glioma, and lung cancer." (PMID 37998329, 2023). "Similarly, it has been shown that the PHLPP1 phosphatase suppressed melanoma metastasis through the dephosphorylation of AKT2 or AKT3 but not AKT1 in human melanoma cells." (PMID 37894325, 2023). "AKT3 amplification is known to occur in melanoma but was not characterized across our panel and could attenuate knockdown efficiency if present, which is consistent with reports in the literature showing robust AKT3 phosphorylation in melanoma." (PMID 37894325, 2023). "We did not detect AKT3 expression in HeLa cells, in contrast to MeWo melanoma cells." (PMID 30755508, 2019). "Live cell-imaging based scratch-wound assays of melanoma cells with stable knock-down of CD271 revealed a significantly reduced cell migration (3.9fold, p = 1.2E-04) and a reduced expression of FGF13, CSPG4, HMGA2 and AKT3 major candidate regulatory genes of melanoma cell migration." (PMID 28852061, 2017). "Indeed, recently it was demonstrated that there is a synergistic co-operation between BRAFV600E and AKT3 in promoting melanoma development and it is therefore possible that TBX3 may also be regulated by AKT3." (PMID 25595898, 2015). "Importantly, multivariate Cox regression analysis validated the power of OVOL1 as an indicator of melanoma-specific survival, independent of tumor thickness according Breslow and age (P < 0.05; expression of AKT3 and TFAP2B did not retain significance in multivariate analysis)." (PMID 28578692, 2017). "However, it will be important to determine whether these are the only mechanisms responsible for the role of TBX3 in melanomas and whether AKT3 can lead to an increase in TBX3 levels regardless of BRAF status." (PMID 25595898, 2015). "In BrafV600E-driven murine melanomas lacking Cdkn2a, AKT1 activation was shown to enhance brain metastasis, whereas AKT2 and AKT3 had a less pronounced effect." (PMID 37894325, 2023). "UACC903 cells, a different human BRAF mutant melanoma cell line, showed a similar lack of beta-galactosidase staining and SASP induction in AKT1 cells, with a modest effect in AKT3 knockout cells as well, showing this phenotype is not cell-line specific." (PMID 35158840, 2022).
melanoma (continued). "Recently, the comparative analysis of gene expression data of CD271+ and CD271− melanoma cells and CD271+ melanocytes identified AKT3 (but not AKT1 or AKT2) among the top up-regulated genes serving as a key mediator of survival." (PMID 32878000, 2020). "AKT3, but not AKT1 or AKT2, mediated the resistance to apoptosis in BRAF-targeted melanoma cells; promoted anchorage-independent growth in triple negative breast cancer; and controlled the VEGF-induced angiogenesis in ovarian cancer." (PMID 31470874, 2019). "Gene expression analysis identified activation of AKT3, but not AKT1 or AKT2, as a major cell survival node upregulated in CD271+ melanoma-initiating cells." (PMID 31118427, 2019). "Nevertheless, our finding that AKT2 knockdown greatly attenuates the metastatic potential of human melanoma cell lines is consistent with previous data, suggesting that PHLPP1 inhibits melanoma metastasis by suppressing the phosphorylation of AKT2 and AKT3 but not AKT1." (PMID 37894325, 2023). "In particular, our custom panel covers all regions of MELP Panel (MAYO Clinic Laboratories), while it does not include AKT3 (exon 5 and 6) and FGFR3 (exon 7, 9, and 14) genes included in the Sentosa® SQ Melanoma Panel (Vela Diagnostics)." (PMID 33317587, 2020). "We now show, that PI3K/AKT signalling via potent oncogenic PIK3CA and AKT3 mutants, is not sufficient to overcome proliferative arrest induced by BRAF/MEK inhibition, but rather enables the survival of a dormant population of MAPK-inhibited melanoma cells." (PMID 30237495, 2018).
glioma (43 papers, 2012 to 2025). A benign or malignant brain and spinal cord tumor that arises from glial cells (astrocytes, oligodendrocytes, ependymal cells). "Dysfunction of AKT3 is implicated in a variety of neurodevelopmental and neurodegenerative brain disorders and tumors, such as glioma." (PMID 37845779, 2023). "have also demonstrated a novel protein (AKT3-174aa) that is encoded by circAKT3 and downregulated in glioma tissues." (PMID 34745938, 2021). "Despite the increased PIK3CA (encoding the PI3K catalytic subunit α) and AKT3 expression in IDH-mutant glioma, the overall AKT activities were statistically lower than those of IDH-wildtype, as indicated by the mean AKT phosphorylation at Ser-473 and Thr-308." (PMID 27852048, 2017). "In contrast, AKT3 was required for anchorage-independent growth of transformed astrocytes and human glioma cells, and AKT3 loss inhibited invasion of transformed astrocytes." (PMID 22680924, 2012). "However, the AKT3-174aa protein encoded by hsa_circ_0017250 can enhance the glioma cell radiosensitivity by inhibiting the phosphorylation of AKTT308." (PMID 34745938, 2021). "Instead, overexpression of Akt3 in a genetic model of PDGF-driven murine glioma or of the clinically relevant activating mutation Akt1-E17K in murine prostate cancer cells facilitated the repair of radiation-induced DNA damage, thereby increasing radiation resistance." (PMID 29562639, 2018). "For instance, circ-AKT3 is under-expressed in glioma tissues; circ-AKT3 overexpression restrains the growth, radioresistance and tumorigenicity of glioma cells." (PMID 35264067, 2022). "The AKT family is divided into three isoforms, namely, AKT1, AKT2, and AKT3, but only AKT3 is described as mandatory for the transformation of astrocytes into glioma cells." (PMID 35004666, 2021). "It was also shown that suppressed expression of Akt3 by RNA interference reduce expression of the Bad phosphorylated form resulting in induced caspase-dependent apoptosis in glioma cells." (PMID 34440090, 2021). "For instance, it has been reported that AKT3-174aa inhibits glioma tumorigenicity by decreasing activated AKT." (PMID 33836754, 2021). "Our results confirm reported investigations and show that AKT1 and AKT2 act as promoters of glioma tumorigenesis, while AKT3 shows a tumor-suppressor role." (PMID 34209611, 2021). "Three circRNAs generated from the AKT3 gene (hsa_circ_0017250, hsa_circ_0112784 and hsa_circ_0112781) are decreased in glioma tissues." (PMID 32171304, 2020). "AKT3-174aa acts as a dominant-negative variant of AKT and inhibits the phosphorylation of AKTT308, thus enhancing the sensitivity of glioma cells to radiation." (PMID 32171304, 2020). "AKT3 mRNA was higher in lower grade gliomas and patients with tumors expressing higher levels of AKT3 mRNA tended to have longer survival which has also been observed in patients with IDH-mutant subtype." (PMID 31842352, 2019). "Except for inducing glioma invasion and anchorage-independent growth, AKT3 was reported to significantly activate DNA repair and resistance to radiation and chemotherapy in GBM cases." (PMID 31470874, 2019). "AS of AKT3 was reported to play important roles in cancers, and AKT3 expression was involved in glioma progression." (PMID 31729991, 2019). "For example, AKT3 is frequently amplified and overexpressed in triple-negative breast cancer and glioma." (PMID 30012111, 2018). "Our data confirm that the U87-MG and U373-MG gliomas express almost negligible amounts of Akt3 when maintained in CSC culture medium." (PMID 29518912, 2018). "In glioma, expression of Akt3 mRNA and protein decreases as the malignancy grade increases, in parallel with increased Akt2 mRNA and protein." (PMID 29518912, 2018). "Recently, genetic analysis on highly malignant glioma induced by Akt3 overexpression revealed a unique increase in gene expression of the DNA repair pathway." (PMID 28483982, 2017).
glioma (continued). "In more recent years, it has become evident that Akt3 is more important than is Akt1 in glioma development and progression." (PMID 26993778, 2016). "Akt1 is the most well characterized isoform of the three, but in recent years, it has become evident that Akt2 and Akt3 are more important than is Akt1 in glioma development and progression." (PMID 26993778, 2016). "It is also known that AKT2 and AKT3 are overexpressed in glioma cells and play a pivotal role in malignant gliomas." (PMID 24967401, 2014). "Similarly, the translation of circAKT3-174 leads to the production of AKT3-174 amino acids (aa) through IRES-mediated translation, and the overexpression of AKT3-174aa has been shown to reduce cell proliferation, radiation resistance, and glioma tumorigenesis." (PMID 40723354, 2025). "AKT3 is overexpressed in glioma cells and has been found to play a critical role in GBM." (PMID 37998329, 2023). "Moreover, the miR-424/AKT3 axis plays roles in glioma progression and invasion by altering the expression of cyclinD1, c-Myc, Bax, and Bcl-2." (PMID 37998329, 2023). "Akt3 is known to be required for anchorage-independent growth of glioma cells." (PMID 34440090, 2021). "For example, AKT3 (1q44) promotes glioma progression and represents a key resistance factor." (PMID 33936159, 2021). "The FBXW7-185aa encoded by circ-FBXW7 can inhibit the proliferation and cell cycle acceleration of glioma, and the circular SHPRH as well as circular AKT3 could encode tumor-suppressed peptides in glioblastoma." (PMID 35281715, 2021). "The data demonstrated that AS of AKT3 was a splicing signature of pST5, which might further reveal the role of AKT3 in glioma." (PMID 31729991, 2019). "Interestingly, in a recent study, the Akt1 isoform was unable to induce PDGF-dependent high-grade glioma in a genetically engineered tumor model, whereas Akt2 and Akt3 isoforms strongly promoted high-grade glioma progression." (PMID 29562639, 2018). "AKT pathway genes AKT2 and AKT3, which contribute to glioma invasiveness and malignancy, and class II myosins, required for glioma invasion and neural stem cell migration, were also progressively up‐regulated as one moves along the backbone of the SF10345 phylogeny." (PMID 27888226, 2016). "Being consistent with our observations, downregulation of AKT3 expression by RNA interference reduces the expression of the phosphorylated form of Bad, resulting in induction of the caspase-dependent apoptosis of glioma cells." (PMID 22494416, 2012). "AKT3 is required for anchorage-independent growth of human glioma cells." (PMID 22494416, 2012). "Interestingly, lncRNA growth arrest-specific 5 (GAS5) functions as a tumor suppressor in glioma cells by alleviating the promoter methylation of miR-424, and consequently increasing the expression of miR-424, and suppressing AKT3 and its targets, cyclinD1, c-Myc, Bax, and Bcl-2." (PMID 37998329, 2023). "In addition, downregulation of AKT3 inhibits invasion and metastasis of glioma." (PMID 32520206, 2020). "Interestingly, glioma induction with the kRas and Akt3 combination required CDKN2A deletion." (PMID 26993778, 2016). "AKT is an established oncogenic kinase with at least three mammalian isoforms AKT1/PKBα, AKT2/PKBβ, and AKT3/PKBγ of which AKT2 plays major pro-oncogenic roles in cancers, including glioma." (PMID 36120909, 2022). "The Kruskal–Wallis test confirmed a significant difference in methylation of all examined genes between glioma types (p < 0.001 for AKT1, AKT3, CHUK, GSK3β, EGFR, PTEN, PIK3AP1; p = 0.032 for AKT2)." (PMID 34209611, 2021). "Data on CNA show that genes AKT2, AKT3, CHUK, EGFR, PIK3AP1, and PTEN show an increase in copy number alterations with the increased glioma grade." (PMID 34209611, 2021). "Exosomes derived from the peripheral blood samples of human glioma patients are reported to carry GBM-specific gDNA of ERBB2, CDK4, AKT3, MDM2, and RB1 genes." (PMID 33137926, 2020).
glioma (continued). "We randomly selected four additional genes (AKT2, AKT3 GRB2 and MMP2) from the “glioma” pathway, other than the validated targets of the key miRNAs.to check for downstream effect of miRNA overexpression." (PMID 29769662, 2018). "In glioma cell lines, AKT2 or AKT3 knockdown inhibited cell growth and induced apoptosis." (PMID 38911393, 2024). "Another AKT3-derived circRNA, hsa_circ_0017250, arises from the circularization of exons 3–7, whose expression is downregulated in highly malignant glioblastoma multiforme (GBM) and glioma-initiating cells." (PMID 37998329, 2023). "The phenotype of Akt3 knockout mice indicates that AKT3 function is critical in brain tissue, thus, perhaps not surprisingly, AKT3 plays a significant role in human gliomas." (PMID 28082369, 2017). "With respect to brain tumors, the level of AKT1 found in glioma cells and tissues was more similar to that found in normal human astrocytes or non-neoplastic regions of the brain; whereas AKT2 levels were increased, and AKT3 levels were decreased." (PMID 22480225, 2012). "Based on the TCGA data, we confirmed that AKT2, but not AKT1 or AKT3, interacts with PDCD4, thus leading to the suppression of PDCD4 in glioma cells." (PMID 33304903, 2020). "Taken together, these data suggest that AKT2, but not AKT1 or AKT3, interacts with and suppresses PDCD4 in the glioma cells." (PMID 33304903, 2020). "Here, we present evidence that AKT2, but not AKT1 or AKT3, interacts with PDCD4 leading to its suppression in glioma cells, and is consistent with the inverse relationship between mRNA levels of AKT2 and PDCD4 observed in the TCGA data analysis." (PMID 33304903, 2020). "AKT3, but not AKT1 or AKT2, was required for the anchorage-independent growth of transformed astrocytes and human glioma cells." (PMID 31470874, 2019). "Similarly in a PDGFB-driven mouse model of low-grade glioma, transgenic expression of AKT2 or AKT3 but not AKT1 greatly accelerated tumour formation." (PMID 28082369, 2017). "Then, because single c-Myc and Cdc20 genes are not sufficient to induce glioma in both CDKN2A+/+ and CDKN2A−/− Ntv-a mice, we explored the role of c-Myc and Cdc20 in glioma development in a RCAS/Ntv-a mouse model using the combination of kRas and Akt3." (PMID 26993778, 2016).
ovarian carcinoma (42 papers, 2011 to 2025). A malignant neoplasm originating from the surface ovarian epithelium. "It is well known that PIK3C2, PIP5K1B, AKT3 are either amplified or mutated in many cancers including ovarian cancer." (PMID 35205706, 2022). "We then assessed the changes in the expression of AKT2, AKT3, and the four glycolytic enzymes caused by silencing endogenous miR-29b expression in the two ovarian cancer cell lines with constitutively high endogenous miR-29b expressions (A2780 and 3AO)." (PMID 26512921, 2015). "AKT2 is linked to metabolic re−programming and invasion, and AKT3 correlates with cancer growth, aggressiveness and chemoresistance in ovarian cancer, suggesting that each isoform may contribute uniquely to the cetrorelix response." (PMID 41458598, 2025). "AKT3 was also highly expressed in primary ovarian cancer, and silencing of AKT3 using shRNA considerably reduced the growth of OC cells." (PMID 37854681, 2023). "Recently, programmed death-ligand 1 (PD-L1) has been identified as the downstream mediator of the miR-654-3p/AKT3 axis in regulating the proliferation and invasion of ovarian cancer cells." (PMID 37998329, 2023). "In ovarian cancer, miR-489 has also been shown to downregulate Akt3, which enhances apoptosis, reduces cell proliferation, and overcomes cisplatin resistance." (PMID 37854681, 2023). "EMX2OS plays an important role in the prognosis of gastric cancer and regulates proliferation and invasion of ovarian cancer through the miR-654-3p/AKT3/PD-L1 regulatory axis." (PMID 37600792, 2023). "We also observed that PIK3C2, PIP5K1B, and AKT3 are highly frequently amplified in the TCGA dataset of ovarian cancer." (PMID 35205706, 2022). "In agreement with our results, Li and colleagues found AKT3 upregulated in a chemotherapy-resistant group of patient-derived xenograft models of ovarian cancer." (PMID 35053468, 2022). "The lncRNA EMX2OS has been reported to affect the proliferation and invasion of ovarian cancer cells by sponging miR-654-3p to regulate AKT3 and the downregulation of EMX2OS results in a poor prognosis of patients with kidney renal clear cell carcinoma." (PMID 35675043, 2022). "Downregulated Akt3 isoform prevents in vitro ovarian cancer cell proliferation, colony formation and migration." (PMID 32489562, 2020). "Reportedly, miR-654-3p targets several genes associated with malignancy, such as P21 in gastric cancer, AKT3 in ovarian cancer, and SYTL2 in osteosarcoma." (PMID 33193697, 2020). "Another study revealed that AKT3 induces cancer progression and growth in a subpopulation of ovarian cancer by mediating the G2-M-transition and therefore an increased cell proliferation." (PMID 31752925, 2019). "Recent investigations indicated that elevated expression of miR-489 blocked cell growth, invasion and EMT by targeting Shp2 in hypopharyngeal carcinoma, SMAD3 in breast cancer, AKT3 in ovarian cancer, and Dek in ovarian cancer, as well as muscle stem cells." (PMID 31083383, 2019). "We conclude that further study of AKT3 activities in ovarian cancer will lead to new insights of the signaling activities, especially those related to the PI3K-AKT pathway." (PMID 29321820, 2017). "In particular, AKT3 has a specific role in the genesis of ovarian cancer through modulation of G2-M phase transition." (PMID 27378931, 2016). "Inhibition of Akt3 had an intermediate phenotype, but also increased growth of ovarian cancer cells." (PMID 27533079, 2016). "Here, we report that miR-29b negatively regulates AKT2/AKT3 expression, causing HK2/PKM2 downregulation and leading to a decreased Warburg effect and slowed ovarian cancer progression." (PMID 26512921, 2015).